PSCA (prostate stem cell antigen)
Description:
May be involved in the regulation of cell proliferation. Has a cell-proliferation inhibition activity in vitro. May act as a modulator of nicotinic acetylcholine receptors (nAChRs) activity. In vitro inhibits nicotine-induced signaling probably implicating alpha-3:beta-2- or alpha-7-containing nAChRs.
Synonyms: lncPSCA; PRO232
Tractability: Antibody: a drug acting on it is in phase 2 or 3 trials; UniProt places it where antibodies can reach, with high confidence; its Gene Ontology location is reachable by antibodies, with high confidence; UniProt predicts a signal peptide or a membrane-spanning region; the Human Protein Atlas places it where antibodies can reach. PROTAC: ubiquitination databases record sites on it.
Gene: Protein-coding gene on chromosome 8 (142,670,308 to 142,682,725, forward strand). Ensembl gene ENSG00000167653.
Subcellular location: Cell membrane
Subcellular location (Human Protein Atlas): Plasma membrane
Pathways (Reactome):
Metabolism of proteins: Post-translational modification: synthesis of GPI-anchored proteins
Gene Ontology:
Molecular function: acetylcholine receptor binding; acetylcholine receptor regulator activity
Biological process: negative regulation of ERK1 and ERK2 cascade; regulation of neurotransmitter receptor activity; acetylcholine receptor signaling pathway
Cellular component: extracellular exosome; plasma membrane; extracellular region; synapse
Genetic constraint (gnomAD): Loss-of-function variants: 7 observed, 5.87 expected, observed/expected ratio (o/e) 1.19, 90% interval 0.66 to 1.87. That is too few expected variants to judge how well the gene tolerates losing a copy. Missense variants: 151 observed, 126.66 expected, observed/expected ratio (o/e) 1.19, 90% interval 1.04 to 1.37. Synonymous variants: 61 observed, 58.63 expected, observed/expected ratio (o/e) 1.04, 90% interval 0.85 to 1.29.
Homologues: Orthologues: chimpanzee PSCA (99% identical), macaque PSCA (94% identical), pig PSCA (78% identical), dog PSCA (75% identical), rabbit PSCA (68% identical), guinea pig PSCA (63% identical), rat Psca (61% identical), mouse Psca (61% identical). Paralogues in human: LY6E (33% identical), GPIHBP1 (31% identical).
Diseases named in the same sentence as PSCA in open-access papers:
PSCA is named in the same sentence as 71 diseases in open-access papers, as found by Europe PMC text mining. Sharing a sentence is not in itself a finding about the gene and the disease. The quoted sentences say what the papers report.
prostate carcinoma (95 papers, 2003 to 2025). A carcinoma that arises from epithelial cells of the prostate gland. "PSCA mRNA is overexpressed in prostate cancer and is associated with tumor stage, grade and androgen-independence which can be used for the diagnosis of prostate cancer." (PMID 38627732, 2024). "Here we present the development and functional characterization of a novel IgG4-based TM, directed to the tumor-associated antigen (TAA) prostate stem cell antigen (PSCA), which is overexpressed in prostate cancer (PCa)." (PMID 35454902, 2022). "For instance, the genetic variation in prostate stem cell antigen (PSCA) gene has been associated with the risk of bladder cancer, pancreatic cancer, and prostate cancer in multiple GWAS studies." (PMID 27876019, 2016). "Recent studies have found that levels of prostate stem cell antigen (PSCA) have higher diagnostic and prognostic value in prostate cancer compared with prostate-specific antigen." (PMID 27783810, 2016). "PSCA overexpression has been associated with an increase in tumor grade, stage, metastasis and recurrence in prostate cancer patients." (PMID 25624885, 2015). "Prostate stem cell antigen was first described as a marker overexpressed in prostate cancer, and was subsequently found to be associated with increasing disease stage and other adverse prognostic features." (PMID 22824379, 2012). "Other TAAs and TSAs, such as alpha-fetoprotein (AFP), which is over-expressed in the majority of hepatocellular carcinoma, and prostate stem cell antigen (PSCA), which is associated with the development of prostate cancer, also showed great synergistic effect with HSP70 in multiple cancers." (PMID 37189349, 2023). "We also identified multiple prostate cancer-associated genes such as cystatin C, PSCA, Cyp2e1, and dermatopontin that were remarkably underexpressed in CTRKO/LPB-Tag-CTRKO as compared to their WT and LPB-Tag counterparts, suggesting that CTR positively regulates these genes." (PMID 32180899, 2020). "The multi‐spheroid model consists of prostate stem cell antigen (PSCA)‐expressing prostate cancer cells and FAP‐producing fibrosarcoma cells in varying ratios." (PMID 40704837, 2025). "Prostate stem cell antigen (PSCA) is also a promising target as IO in prostate cancer, particularly in metastatic and treatment-resistant forms, as it is not present in normal prostate cells." (PMID 40260236, 2025). "Prostate cancer is rich in tumor associated antigens such as, but not limited to, PSMA, PSCA, hK2, and STEAP1 and there is strong biologic rationale for employment of T-cell redirecting BiTEs within the prostate cancer disease space." (PMID 38801069, 2024). "ISH analysis has shown that PSCA mRNA is expressed in more than 80% of prostate cancers and this expression is much higher than the adjacent normal glands." (PMID 38627732, 2024). "The membrane protein prostate stem cell antigen (PSCA) is highly overexpressed in most primary prostate carcinoma (PCa) cells and in metastatic and hormone refractory tumor cells." (PMID 37298374, 2023). "Prostate stem-cell antigen (PSCA) is another tumor antigen that is overexpressed in prostate cancer." (PMID 37762648, 2023). "First, it expresses multiple tumor-associated antigens: e.g., prostate-specific antigen (PSA), prostate-specific membrane antigen (PSMA), and prostate stem cell antigen (PSCA), which provide a reliable therapeutic target for prostate cancer immunotherapy." (PMID 36925917, 2023). "Due to its overexpression on the surface of prostate cancer (PCa) cells, the prostate stem cell antigen (PSCA) is a potential target for PCa diagnosis and therapy." (PMID 35454902, 2022). "To date, the most extensively investigated TAAs preclinically and clinically in the context of prostate cancer are prostate stem cell antigen (PSCA), epithelial cell adhesion molecule (EpCAM) and prostate-specific membrane antigen (PSMA)." (PMID 35158771, 2022).
prostate carcinoma (continued). "GPI-anchored LY6 family member PSCA is most commonly attributed to prostate stem cells and prostate cancer; however, its overexpression in pancreatic cancer and limited expression in normal pancreatic cells is also well recognized." (PMID 33613843, 2021). "PSCA is also expressed in prostate cancer metastases and in prostate-unrelated carcinomas such as pancreatic adenocarcinoma, renal clear-cell carcinoma, transitional cell carcinoma, and glioblastoma." (PMID 34066833, 2021). "In some former studies, upregulation of PSCA in prostate cancer was significantly correlated with progression to androgen independence, biochemical recurrence, and/or distant metastases." (PMID 33029516, 2020). "Elevated levels of prostate stem cell antigen (PSCA) has been observed in more than 80% of prostate cancer tissues and all cases of bone metastatic prostate cancer in patients." (PMID 32521759, 2020). "Prostate stem cell antigen (PSCA) is a cell-surface antigen expressed in normal prostate and overexpressed in prostate cancer (PC) tissues." (PMID 32048062, 2020). "For example, in prostate cancer, a biCAR was constructed with two prostate cancer antigens (prostate-specific membrane antigen and prostate stem cell antigen), the expression of which are also found on normal tissues." (PMID 31754328, 2019). "PSCA (prostate stem cell antigen), a recognized surface marker of prostate cancer, was increased 52-fold." (PMID 31009485, 2019). "Prostate Stem Cell Antigen (PSCA) is frequently expressed in prostate cancer but its exact function is unclear." (PMID 29855276, 2018). "Prostate stem cell antigen (PSCA) is a serine protease expressed in the basal cells of normal prostate cells and is overexpressed in approximately 80% of prostate cancers." (PMID 30031396, 2018). "Prostate stem cell antigen (PSCA), a member of the Ly‐6 family is overexpressed in prostate cancer cells." (PMID 28660664, 2017). "Prostate stem cell antigen (PSCA) has been suggested as biomarker and therapeutic target for prostate cancer." (PMID 28903367, 2017). "Prostate stem cell antigen (PSCA) expression has been shown to correlate with prostatic carcinogenesis and prostate cancer (PCa) progression." (PMID 26981049, 2016). "They confirmed that the prostate stem cell antigen (PSCA) expression was prostate specific and it was overexpressed in the majority of the prostate cancers." (PMID 26981049, 2016). "CV9103 is a prostate-cancer vaccine containing self-adjuvanted mRNA (RNActive®) encoding the antigens PSA, PSCA, PSMA, and STEAP1." (PMID 26082837, 2015). "Prostate stem cell antigen (PSCA) was originally identified as a gene that is overexpressed in prostate cancer, and correlates with prostate cancer progression and prognosis." (PMID 25624885, 2015). "Elevated levels of PSCA have been reported in over 80% of prostate cancer specimens and in all cases of bone metastasis from prostate cancer patients." (PMID 24391668, 2013). "The prostate stem cell antigen (PSCA) gene was originally identified through an analysis of genes upregulated in the human prostate cancer LAPC-4 xenograft model." (PMID 23984394, 2013). "Increased expression of Prostate Stem Cell Antigen (PSCA) is correlated with development of malignant human prostate cancer, while studies in mouse models suggest that decreased PSCA levels promote prostate cancer metastasis." (PMID 22536409, 2012). "The prostate stem cell antigen (PSCA) is broadly expressed on the surface of prostate cancer (PCa) cells." (PMID 22761679, 2012). "Over the past years, several prostate cancer associated antigens have been reported including prostate specific antigen (PSA), prostate-specific membrane antigen (PSMA), prostate stem cell antigen (PSCA) and six transmembrane epithelial antigen (STEAP)." (PMID 20181099, 2010).
prostate carcinoma (continued). "In this regard, prostate stem cell antigen is a good example because although it is being tested as a therapeutic target for the treatment of prostate cancer, it is also overexpressed in pancreatic cancer." (PMID 19360088, 2009). "Glutamate carboxypeptidase II (prostate-specific membrane antigen), identified with 26 peptides, and prostate stem-cell antigen are other strong indicators of prostate cancer." (PMID 16709260, 2006). "Similarly, PSCA is upregulated in many prostate cancers and correlates with higher tumor grade and poor prognosis, but its expression is not restricted to the prostate." (PMID 41303628, 2025). "Furthermore, prostate stem cell antigen (PSCA) is a tumor-related molecule that is expressed in 90% of prostate cancer tissues, but also in 60–70% of normal prostate tissues." (PMID 36831396, 2023). "Although the expression of PSCA is upregulated in most of prostate cancers, its biological role in prostate cancer remains unclear." (PMID 36497465, 2022). "Prostate cancer cells express numerous tumor-associated antigens (TAA), such as PSA, prostate-specific membrane antigen (PSMA), prostatic acid phosphatase (PAP), and prostate stem cell antigen (PSCA), which are predominantly expressed in prostate tissue." (PMID 33477569, 2021). "Similar to the expression of PSCA in the prostate cancer specimens, intensive IHC expression of NSE was observed in patients with a higher Gleason score, advanced pT stage, and metastasis in the present study, in agreement with the findings from previous studies." (PMID 33029516, 2020). "Importantly, the treatment with genistein together with other two flavonoids belonging to the class of flavones (luteolin) and flavonols (quercetin) inhibited the expression of PSCA at the mRNA and protein level in prostate cancer DU145 cells." (PMID 32521759, 2020). "Therefore, the expression of the prostate stem cell antigen can be an assistant measure for the clinical diagnosis and progressivity assessment of prostate cancer." (PMID 33029516, 2020). "Similarly, immunization with VEE particles expressing prostate stem cell antigen (PSCA) induced long-term protection against prostate cancer in prostate cancer-prone transgenic adenocarcinoma mouse prostate (TRAMP) mice." (PMID 30551668, 2018). "PSCA is a newly discovered tumor-associated antigen with high specific expression in various types of prostate cancer and metastatic cancer, and its expression is not reduced with tumor progression." (PMID 27783810, 2016). "Prostate stem cell antigen (PSCA) is upregulated in prostate cancer tissues." (PMID 24330823, 2013). "Our results also suggest multiple roles for YY1 in prostate cancer which may contribute to disease progression by modulation of genes such as PSCA." (PMID 22536409, 2012). "Prostate stem cell antigen (PSCA) is a membrane glycoprotein that is expressed in prostate cancer." (PMID 24213111, 2011). "Currently identified tumor-associated antigens (TAAs) for prostate cancer (PCa) include prostate acid phosphatase (PAP), transient receptor potential (Trp)-p8, prostate-specific membrane antigen (PSMA), prostate stem cell antigen (PSCA), and prostate-specific antigen (PSA)." (PMID 39996908, 2025). "PSCA represents an associated glycophosphatidylinositol (GPI)-anchored cell surface antigen, which is expressed in normal prostate-specific tissue and overexpressed in prostate cancer specimens including both high-grade prostatic intraepithelial neoplasia and androgen-dependent/independent tumors." (PMID 34066833, 2021). "Firstly, prostate cancer can express multiple tumor-associated antigens necessary in triggering anti-tumor immune response [such as prostate-specific antigen (PSA), prostatic acid phosphatase (PAP), prostate-specific membrane antigen (PSMA), and prostate stem cell antigen (PSCA)]." (PMID 28460462, 2017).
prostate carcinoma (continued). "Antibody-based prostate cancer therapies currently rely on a limited repertoire of targets, including prostate-specific membrane antigen (PSMA) and prostate stem cell antigen (PSCA)." (PMID 41303628, 2025). "Other targets seem to be specific for prostate cancer, for instance, PSA (official symbol KLK3 [P07288]), PSMA (official symbol FOLH1 [Q04609]), and PSCA [O43653]." (PMID 39595075, 2024). "In prostate cancer, TAAs such as PSMA, prostate stem cell antigen (PSCA), prostate-specific antigen (PSA), and epithelial cellular adhesion molecule (EpCAM) are being investigated." (PMID 37420216, 2023). "Target antigens for prostate cancer CAR T cell therapy include prostate-specific antigen, prostate acid phosphatase, prostate-specific membrane antigen (PSMA), prostate stem cell antigen (PSCA), and epithelial cell adhesion molecule (EpCAM)." (PMID 37173782, 2023). "PSCA is a TAA upregulated in several major cancers, including prostate cancer, urinary bladder cancer, renal cell carcinoma, pancreatic cancer, ovarian mucinous tumor and NSCLC." (PMID 36817127, 2023). "Prostate stem cell antigen (PSCA), a glycosylphosphatidylinositol-anchored cell membrane glycoprotein, is involved in not only prostate cancer but also gastric cancer and DU in different ethnicities." (PMID 36678166, 2023). "Currently, three main targets of CAR-T therapy for prostate cancer research are prostate specific membrane antigen (PSMA), prostate stem cell antigen (PSCA), and epithelial cell adhesion molecule (EpCAM)." (PMID 35205714, 2022). "With PCa, the expressed antigens by prostate carcinoma are prostate-specific antigen (PSA), PSMA, prostatic acid phosphatase (PAP), and prostate stem cell antigen (PSCA)." (PMID 33440664, 2021). "For prostate cancer, CARs binding to the prostate-specific membrane antigen (PSMA), the prostate stem cell antigen (PSCA), and EpCAM have been tested in preclinical and phase I clinical trials." (PMID 32326073, 2020). "For the active targeting of prostatic cancer cells, nanostructures functionalized with antibodies for prostatic specific membrane antigen (PSMA) and prostate stem cell antigen (PSCA) antigens were considered." (PMID 33238455, 2020). "Two prostate-specific antigens are being explored in Phase I trials in prostate cancer thus far using PSMA and prostate stem cell antigen (PSCA), which is primarily expressed in prostate cancer cells and is expressed in advanced prostate cancer." (PMID 32630247, 2020). "Prostate stem-cell antigen (PSCA), a glycosylphosphatidylinositol (GPI)-anchored protein overexpressed in prostate cancer cells, has also been exploited as a possible target for immunotherapy." (PMID 29423071, 2018). "In prostate cancer, PSMA and prostate stem cell antigen (PSCA) are the mostly used conjugated antibodies, both of which are highly expressed in prostate cancer cells." (PMID 28400729, 2017). "Checkpoint inhibitors or monoclonal antibodies have been used to treat prostate cancer due to its specificity in honing in on the tumor through prostate-specific membrane antigen (PSMA) and prostate stem cell antigen (PSCA)." (PMID 28239502, 2017). "In this study, we evaluated this interesting approach for CTLA4 enhancement on prostate stem cell antigen (PSCA)-specific immune responses and its anti-tumor effects in a prostate cancer mouse model." (PMID 27783810, 2016). "The prostate stem cell antigen (PSCA) is a protein expressed on the surface of prostate epithelial cells as well as in primary and metastatic prostate cancer cells and therefore a promising target for immunotherapy of prostate cancer." (PMID 24438073, 2014). "Prostate stem cell antigen (PSCA) is a prostate tissue-restricted antigen highly expressed on primary and metastatic prostate cancer cells." (PMID 24438073, 2014).